CD4 (CD4 molecule)
Diseases named in the same sentence as CD4 in open-access papers (continued):
Sharing a sentence is not in itself a finding about the gene and the disease.
inflammatory bowel disease (continued). "In active inflammatory bowel disease, P2Y6 expression was highly upregulated in activated CD4+ and CD8+ T cells infiltrating intestinal mucosa." (PMID 25243587, 2014). "CD4+ T cell responses against oral antigens can develop in inflammatory bowel disease (IBD) patients, which may modulate disease." (PMID 23936123, 2013). "Increased levels of lymphocyte-activation antigens, including CD98, have been found at the cell surface of intestinal B cells, CD4+ T cells and CD8+ T cells isolated from patients with inflammatory bowel disease." (PMID 19065266, 2008). "The B. fragilis PSA can suppress inflammatory bowel disease and experimental autoimmune encephalomyelitis (EAE) through activating helper T cells that express the surface protein CD4 (CD4+ T cells) through a mechanism dependent on the major histocompatibility complex class II (MHCII)." (PMID 41150213, 2025). "For example, in inflammatory bowel disease (IBD), studies have shown that the CD4:CD8 ratio in intestinal tissues may play a significant role in the pathogenesis of the disease." (PMID 41149805, 2025). "In a similar gene-transfer approach, high IL-10 production is induced by lentiviral transduction into CD4+ T cells (CD4LV-IL10) to produce allogenic type 1 regulatory T cells (Tr1 cells) for “off-the shelf” GvHD and inflammatory bowel disease (IBD) treatment in clinical trials led by Tr1X Bio." (PMID 41246323, 2025). "Mice lacking BCL11B in double‐positive thymocytes develop inflammatory bowel disease, with massive pro‐inflammatory cytokine‐producing CD4+ T cells infiltrating in the colon." (PMID 39092763, 2024). "Since CD4+CD25+FoxP3+ Treg lymphocytes have been described to play an important role in the development and control of inflammatory bowel disease, we next analysed the representation of this population in the spleen and the MLNs of the different groups of animals after in vitro stimulation." (PMID 39769391, 2024). "CD38bright CD8+ T cells can predict acute graft-versus-host disease, phenotypic changes in CD38+ CD4+ T cells can predict the severity of inflammatory bowel disease, and CD38 expression in CD4+, CD8+, or CD25+ T cells is significantly higher in SLE patients than in healthy controls." (PMID 37445926, 2023). "Therefore, we showed that the CD4+CD25-CD45Rbhigh T cell adoptive transfer model, also called the adoptive transfer inflammatory bowel disease (IBD) model, is a good disease model for investigating inflammation of the oral mucosa." (PMID 36389752, 2022). "Indeed, regulatory CD4+CD25+Foxp3+ T cells are abundant in the colonic mucosa, and breakdown of these local mechanisms of immune regulation and gut homeostasis has been associated with the development of inflammatory bowel diseases (IBD)." (PMID 35919733, 2021). "In terms of regulation of CD4+ T cells, JKAP is reported to repress CD4+ T‐cell activation as well as its differentiation into Th1 and Th17 cells in systemic lupus erythematosus nephritis and inflammatory bowel disease." (PMID 34289265, 2021). "Inflammatory bowel disease (IBD) is a chronic disorder manifested as Crohn’s disease (CD) and ulcerative colitis (UC) characterized by intestinal inflammation and involves a dysregulated immune response against commensal microbiota through the activation of CD4 T helper cells." (PMID 32403220, 2020). "The ability of H. bilis to incite CD4+ T cell responses against the microbiota, but not itself, is a novel finding that may partly explain why no single microorganism or immune response against particular microbiota members has ever been associated with inflammatory bowel diseases." (PMID 29255158, 2017). "CD4+ and CD8+ T cells played important role in inflammatory bowel disease." (PMID 27128484, 2016).
inflammatory bowel disease (continued). "The human dataset comprised genotype and corresponding expression data from three purified leukocyte subsets (monocytes, and CD4 and CD8 T cells) isolated from the peripheral blood of 59 patients with inflammatory bowel disease (see Supplementary Methods for full details of the cohort)." (PMID 26504141, 2016). "Inflammatory bowel disease (IBD) is comprised of ulcerative colitis and Crohn’s disease, which differ in the anatomical distribution of lesions, depth of tissue inflammation, and the CD4+ T cell subsets involved." (PMID 26230654, 2015). "CD4+CD25highFoxp3+ regulatory T cells play a central role in the maintenance of tolerance in the gut and may also contribute to inadequate counterregulation in inflammatory bowel disease (IBD)." (PMID 25144293, 2014). "Furthermore, the authors demonstrated that CD4+CD25+ Tregs with FOXP3 transduction inhibited the proliferation of lymphocytes and the occurrence of inflammatory bowel disease and gastritis in mice." (PMID 24944616, 2014). "As an example, in a mouse animal model of inflammatory bowel disease (IBD), the beneficial effect of injected human adipose derived MSCs (hASCs) on the clinical and histological scores of mice was associated with an increased number of CD4+CD25+Foxp3+ and CD4+IL10+ cells in the lymph nodes." (PMID 23734780, 2013). "Furthermore, TOB1 not only inhibits the proliferation of Th17 cells, but in inflammatory bowel disease, it also induces the expression of ID2 in CD4+ T cells via SMAD4/5 signaling, which suppresses the conversion of CD4+ T cells into Th1/Th17 cells, thereby inhibiting mucosal inflammation." (PMID 38617839, 2024). "Furthermore, data from inflammatory bowel disease and preclinical models suggest that RUNX3 induced polarization of CD4+ cells towards a CD4+ CTL phenotype may be especially important in the gut epithelium." (PMID 36900240, 2023). "Given that ILCs are CD4-negative cells and the expression of α4β7 integrin on ILCs in the mucosa of patients with inflammatory bowel disease is low25, ILCs may play a central role in the pathogenesis of UC in patients who show a poor response to vedolizumab." (PMID 37985889, 2023). "In the study of autoimmune disease models such as inflammatory bowel disease (IBD), it was found that the expression and activity of K2P5.1 were significantly upregulated in the CD4+ T cells of the model." (PMID 36187789, 2022). "We however did not confirm a previous result of high expression of IL-17 by CD73+ CD4+ T cells, possibly because we used PMA/Ionomycin stimulation of cells from healthy adult controls, compared to anti-CD3/CD28 stimulation of cells from inflammatory bowel disease patients in the previous study." (PMID 33477692, 2021). "A better understanding of the function of CD4+ TRM cells is crucial for the development of both effective vaccination against pathogens and new therapeutic strategies for intractable inflammatory diseases, such as inflammatory bowel diseases and chronic allergic diseases." (PMID 33968018, 2021). "CD4+ T cells are one of the key adaptive immune cells that play an important role in several autoimmune diseases like multiple sclerosis (MS), experimental autoimmune encephalomyelitis (EAE), inflammatory bowel disease (IBD), and collagen-induced arthritis (CIA)." (PMID 26257732, 2015). "However, conditions like Crohn's disease (CD) or ulcerative colitis (UC), the main forms of inflammatory bowel diseases (IBD), are related to an excessive and uncontrolled immune response against normal microbiota, through the activation of CD4+ T helper (Th) cells." (PMID 25101191, 2014). "Paeoniflorin, a monoterpene glycoside extracted from the roots of Paeonia lactiflora, can significantly promote the differentiation of CD4+CD25+Foxp3+ Tregs and suppress the production of Th17 cells, restoring the Th17/Treg balance for the treatment of inflammatory bowel disease (IBD)." (PMID 41458964, 2025).
inflammatory bowel disease (continued). "Complementary in vitro evidence confirms butyrate’s preferential differentiation of naïve CD4 + T cells from Inflammatory bowel disease (IBD) patients toward Tregs rather than Th17 lineages - a shift proven critical for restoring mucosal immune tolerance." (PMID 40873717, 2025). "Moreover, IECs isolated from patients with inflammatory bowel disease (IBD) expressed MHC II, CD80 and CD86 and were found capable of inducing CD4 T cell proliferation and IFNγ secretion." (PMID 31316504, 2019). "Consistent with a protective role of IL-10 in inflammatory bowel diseases (IBD), effector CD4+ T cells from Crohn’s disease patients were defective in Notch/STAT3-induced IL-10 production and skewed towards an inflammatory Th1/17 cell phenotype." (PMID 35169232, 2022). "It has been reported that JKAP regulates the functions of T cells, for instance, JKAP can inhibit the CD4+ T cell activation and differentiation to Th1 and Th17 cells in peripheral blood mononuclear cell (PBMC) collected from patients with active inflammatory bowel disease (IBD)." (PMID 33083958, 2021). "As for the TRM in other tissues, the maintenance of intestinal CD4 TRM may be related to Hobit and Blimp-1, and the deletion of these molecules results in functional impairment of CD4 TRM in the murine model of inflammatory bowel disease (IBD)." (PMID 34884736, 2021).
leukemia (265 papers, 2005 to 2026). A malignant (clonal) hematologic disorder, involving hematopoietic stem cells and characterized by the presence of primitive or atypical myeloid or lymphoid cells in the bone marrow and the blood. "Together, our data suggests that FLT3-ITD+ leukemia-associated cDCs polarize CD4+ T cells into Th17 subsets, a population that has been shown to be negatively associated with survival in solid tumor contexts." (PMID 38495876, 2024). "Long-term cellular and humoral immunity associated with graft-versus-leukemia (GVL) effects were evaluated through detecting the percentage of CD4+ T cells, IgG, IgM and IgA concentrations, and performing tumor challenge experiment." (PMID 39776911, 2024). "KRAS knockout is embryonically lethal and KRASG12D knockin mutation caused CD4+/CD8+ double positive T lymphoblasts leukemia in the mice model." (PMID 38898200, 2024). "CLIP-positive AML blasts have been shown to evade CD4 T cell killing by blocking the presentation of endogenous leukemia-associated antigens and the induction of a leukemia-specific T-cell response." (PMID 38418901, 2024). "In CBT specifically, CD4+ T-cell reconstitution has been positively associated with improved overall and leukemia-free survival in children and adults." (PMID 37780051, 2023). "Altogether, the evidence suggests that CD4-associated pathways represent a valuable target for leukemia management, which warrants further investigation and exploration." (PMID 37736548, 2023). "After constructing prognostic gene models in leukemia, we found that CD4, VDR and LST1 were the most significant prognostic risk genes." (PMID 37736548, 2023). "These CD4 T cell subpopulations were also significantly increased in the metastatic lesions of the livers originated from HVEM deficient leukemia cells compared to that of HVEM WT tumors." (PMID 37033927, 2023). "The characteristics of leukemia-associated CD4+ T cells are similar to those of SA-T cells found in normal aged mice, encompassing senescence characteristics, indicating that systemic leukemia allows a swift increase in CD4+ T cell senescence." (PMID 37489425, 2023). "In this study, we collected LEXs derived from mouse leukemia L1210 cells transduced with a lentiviral vector encoding CD80 and CD86 and investigated the anti-leukemia immunity of LEX-CD8086-targeted CD4+ T cells in vitro and in vivo." (PMID 36466863, 2022). "We further show that TR1 cell-mediated control of TCL1 leukemia requires IL-10 receptor (IL-10R) signaling, as Il10rb-deficient CD4+ T cells showed impaired antileukemia activity." (PMID 33526861, 2021). "Regulatory T cells, previously shown to associate with poor BCR-ABL leukemia control, were present at higher frequencies among CD4+ splenocytes of vitamin A deficient vs. sufficient mice." (PMID 32047189, 2020). "Supporting the correlation between mutational pattern and leukemic LGL phenotype, STAT5b mutations were specifically found only in CD4+ T-LGL leukemia." (PMID 28977911, 2017). "At variance to STAT3 mutated patient, analyzing CD16, CD56, CD57 cell markers no specific immunophenotype distinguishing STAT5b mutated from wild type patients was evidenced among CD4+ T-LGL leukemia." (PMID 28977911, 2017). "Vbeta 13.1 prevalence observed in CD4+ T-LGL leukemia was similarly found in STAT5b mutated patients (2/5, 40%)." (PMID 28977911, 2017). "Nonetheless, it is obvious that HTLV-1 infection dramatically increases the risk of leukemia generation from peripheral CD4 T-cells, in which the incidence of leukemia is quite low." (PMID 23198153, 2012). "Notably, CD4+ CAR-T cell persistence was associated with long-term survival in leukemia patients, but on the other hand, CD4+ CAR-T cells are implicated in cytokine release syndrome." (PMID 39893177, 2025).
leukemia (continued). "We ask the question whether a higher FOXP3 mRNA expression in recipient CD4+ T cells obtained from peripheral blood prior to myeloablative conditioning was associated with an increased risk of posttransplant leukaemia relapse." (PMID 36051013, 2022). "Leukemia-associated CD4+ T cells exhibit characteristics to those of SA-T cells occurring in normal aged mice, including senescence features, indicating that systemic leukemia causes a rapid progression of CD4+ T cell senescence." (PMID 30603051, 2018). "However, recent studies suggest that another gene called HBZ (HTLV-1 bZIP factor) which is encoded by the minus-strand of the HTLV-1 can cause an ATL-like CD4 leukemia in mice." (PMID 29018415, 2017). "Moreover, CD4+ memory activated T cells significantly decreased in the ‘High-risk’ groups; it may attenuate the ferroptosis of leukemia induced by cytotoxic T cells according to previous reports." (PMID 34906116, 2021). "Because C/EBPα plays a role in the accumulation of PD1+ CD4+ T cells in old mice, we hypothesized that loss of C/EBPα in the lymphoid compartment may affect the leukemia-dependent accumulation of PD-1+ CD4+ T cells and more importantly, the development of leukemia per se." (PMID 24404186, 2014). "The levels of CXCR3 were higher in CD4+CD8+ DP cells of leukemia-bearing mice compared with control animals." (PMID 41129238, 2026). "The b3a2 TCR specifically recognizes MHC class II and was originally derived from a CD4+ T cell targeting the BCR-ABL fusion protein in leukemia." (PMID 41484912, 2026). "Here, we demonstrate that a novel process of dynamic NKG2D expression by both CD4– and CD4+ iNKT cell subsets allows targeting of leukemia cells with variable expression of CAR antigens more efficiently than by CAR T cells, in an NKG2D-dependent manner." (PMID 40898981, 2026). "In vitro assays confirm the ability of CD4+ T cells from leukemia‐responsive mice to promote robust maturation of naïve bone marrow DC in the presence of non‐immunogenic leukemia antigens." (PMID 39727041, 2025). "In a recent study using a murine Arf−/−Bcr-Abl1 mouse model, BCR::ABL1-specific CD4+ memory T cells played a protective role, with T cell depletion drastically increasing leukemia outgrowth after dasatinib or cytotoxic chemotherapy." (PMID 40503229, 2025). "When we analyzed Tregs numbers in clinical samples, we found that the total number of CD4+ T cells was small (3.7% on average) due to expansion of leukemia cells." (PMID 40858576, 2025). "Although limited by our sample size, CosMx data showed potential post-ICI TWEAK signaling between leukemia cells and adjacent DCs, naïve CD4 T cells, and granulocyte-monocyte progenitor cells." (PMID 40632867, 2025). "Responder patients 2 and 6 and nonresponder patient 3 exhibited a consistently significant trend of enrichment in the naïve CD4+ T cell population at baseline around leukemia cells compared with the end of the second treatment cycle." (PMID 39975227, 2025). "In a BCR::ABL+ ALL mouse model, PD-L1 blockade led to clonal expansion of leukemia-specific CD4+T cells with a helper/cytotoxic phenotype, while reducing exhaustion marker expression." (PMID 40503229, 2025). "Responder patients 2 and 6 and nonresponder patient 3 exhibited a consistently notable trend of enrichment in the naïve CD4+ T cell population at the baseline around leukemia cells compared with the end of the second treatment cycle." (PMID 40632867, 2025). "NPM1 mutation-specific CD8+ T cells can directly lyse leukemia cells harboring NPM1 mutations, whereas CD4+ T cells support CD8+ T cell function and induce HLA class II-mediated anti-tumor cytotoxic responses." (PMID 40861464, 2025). "BPDCN was previously known as CD4+ CD56+ cutaneous lymphoma, blastic natural killer cell lymphoma/leukemia, agranular CD4+ natural killer cell leukemia, and agranular CD4+ CD56+ hematodermic neoplasm." (PMID 39858003, 2025).